COL5A1 (collagen type V alpha 1 chain)
Description:
Type V collagen is a member of group I collagen (fibrillar forming collagen). It is a minor connective tissue component of nearly ubiquitous distribution. Type V collagen binds to DNA, heparan sulfate, thrombospondin, heparin, and insulin.
Synonyms: EDSC; EDSCL1; FMDMF
Tractability: Antibody: its Gene Ontology location is reachable by antibodies, with high confidence; UniProt places it where antibodies can reach, with medium confidence; UniProt predicts a signal peptide or a membrane-spanning region. PROTAC: ubiquitination databases record sites on it. Other modalities: an approved drug acts on it.
Gene: Protein-coding gene on chromosome 9 (134,641,803 to 134,844,843, forward strand). Ensembl gene ENSG00000130635.
Subcellular location: Secreted, extracellular space, extracellular matrix
Subcellular location (Human Protein Atlas): Vesicles; Predicted to be secreted
Pathways (Reactome):
Extracellular matrix organization: Assembly of collagen fibrils and other multimeric structures; Collagen biosynthesis and modifying enzymes; Collagen chain trimerization; Collagen degradation; ECM proteoglycans; Fibronectin matrix formation; Integrin cell surface interactions; Non-integrin membrane-ECM interactions; Syndecan interactions
Developmental Biology: Developmental Lineage of Pancreatic Ductal Cells; NCAM1 interactions
Signal Transduction: MET activates PTK2 signaling; Signaling by PDGF
Disease: Attachment of bacteria to epithelial cells
Gene Ontology:
Molecular function: extracellular matrix structural constituent conferring tensile strength; heparin binding; platelet-derived growth factor binding; protein binding; proteoglycan binding; integrin binding; extracellular matrix structural constituent
Biological process: cell adhesion; cell migration; collagen biosynthetic process; collagen fibril organization; eye morphogenesis; integrin biosynthetic process; negative regulation of endodermal cell differentiation; skin development; supramolecular fiber organization; wound healing, spreading of epidermal cells; skeletal system morphogenesis
Cellular component: collagen type V trimer; extracellular matrix; extracellular region; collagen type XI trimer; endoplasmic reticulum lumen; basement membrane; collagen trimer
Genetic constraint (gnomAD): Loss-of-function variants: 15 observed, 258.91 expected, observed/expected ratio (o/e) 0.0579, 90% interval 0.038 to 0.089. The upper end of that interval is the gene's LOEUF score, 0.089, which puts it in group 1 of 6, group 1 being the genes least tolerant of losing a copy. Missense variants: 1,998 observed, 2,582.3 expected, observed/expected ratio (o/e) 0.77, 90% interval 0.75 to 0.8. Synonymous variants: 989 observed, 1,008.6 expected, observed/expected ratio (o/e) 0.98, 90% interval 0.93 to 1.03.
Gene-disease validity (ClinGen):
ClinGen rates the evidence that COL5A1 causes each of these diseases.
Ehlers-Danlos syndrome, classic type (autosomal dominant): Definitive. Ehlers-Danlos syndrome, classic type (cEDS) is a form of Ehlers-Danlos syndrome that affects the connective tissue and is characterized by skin hyperextensibility, widened atrophic scars and joint hypermobility.
Homologues: Orthologues: chimpanzee COL5A1 (99% identical), macaque COL5A1 (99% identical), mouse Col5a1 (94% identical), rat Col5a1 (94% identical), dog COL5A1 (94% identical), guinea pig COL5A1 (94% identical), pig COL5A1 (92% identical), tropical clawed frog col5a1 (81% identical), zebrafish col5a1 (77% identical). Paralogues in human: COL11A1 (74% identical), COL11A2 (66% identical), COL5A3 (56% identical), COL2A1 (36% identical), COL27A1 (36% identical), COL1A1 (35% identical), COL24A1 (34% identical), COL5A2 (34% identical), COL3A1 (33% identical), COL4A5 (33% identical), COL4A1 (32% identical), COL1A2 (32% identical), and 25 more.
Diseases named in the same sentence as COL5A1 in open-access papers:
COL5A1 is named in the same sentence as 178 diseases in open-access papers, as found by Europe PMC text mining. Sharing a sentence is not in itself a finding about the gene and the disease. The quoted sentences say what the papers report.
Ehlers-Danlos syndrome (35 papers, 2006 to 2025). The Ehlers–Danlos syndromes (EDS) are a clinically and genetically heterogeneous group of heritable connective tissue disorders (HCTDs) characterized by joint hypermobility, skin hyperextensibility, and tissue fragility. "COL5a1/a2 are associated with several diseases, including Ehlers-Danlos syndrome, which is characterised by very elastic skin, weakened blood vessels, and joint hypermobility." (PMID 38997817, 2024). "Literature has reported that mutation of COL5A1 gene is associated with Ehlers-Danlos syndrome (EDS), a genetic disorder mainly characterized with irregular collagen fibrils." (PMID 35241120, 2022). "Defects in COL5A1 are associated with Ehlers-Danlos syndrome, which can present cardiac involvement, although this is uncommon." (PMID 36008935, 2022). "Mutations in COL5A2 or COL5A1 account for over 90% of the cases of the classic Ehlers-Danlos syndrome, characteristic for joint hypermobility." (PMID 35588128, 2022). "Pathogenic variants in COL12A1, COL6A1, COL1A1, and COL5A1 have been described in individuals with different subtypes of the connective tissue disorders Ehlers-Danlos Syndrome and osteogenesis imperfecta." (PMID 33649486, 2021). "In patients with Ehlers-Danlos syndrome, mutations in the COL5A1 gene lead to a decrease in corneal thickness and the density of collagen fibrils, similar to the changes observed in keratoconus." (PMID 34625056, 2021). "COL5A1 gene mutations are also strongly linked to classic Ehlers-Danlos syndrome, a severe heritable connective tissue disease presents with laxity and fragility of connective tissues, especially tendons and ligaments." (PMID 29632650, 2018). "This was analyzed in detail in the case of the c.655-2A>G mutation in the COL5A1 gene that mutations were found in Ehlers-Danlos syndrome (EDS) patients." (PMID 29680930, 2018). "A similar result of maintaining corneal transparency with increasing fibril diameter and regular packing was observed in the Col5a1+/− haploinsufficient mouse model and in patients with classic Ehlers-Danlos syndrome (EDS), associated with a type V collagen mutation." (PMID 39000162, 2024). "In particular variants in COL5A1, which encodes a subunit of type V collagen, are associated with Ehlers-Danlos syndrome, a connective tissue disorder that may also involve the auditory system, including conductive and sensorineural hearing loss." (PMID 36656851, 2023). "Mutations in the COL5A1 gene are the most common cause of Ehlers-Danlos syndrome." (PMID 34625056, 2021). "The COL5A1 gene is the most explored genetic locus in relation to tendon and ligament injuries, while mutations in the COL5A1 gene have been identified in Ehlers-Danlos syndrome, a disease characterised by joint hypermobility, laxity and muscle hypotonia." (PMID 29143592, 2017). "While FBN1 is a well-established gene for Marfan syndrome, COL5A1, primarily associated with Ehlers-Danlos syndrome (EDS), has been reported in cases where EDS and Marfan syndrome are difficult to distinguish due to overlapping connective tissue abnormalities." (PMID 41411243, 2025). "Symptomatic joint hypermobility is a common clinical feature of classic Ehlers-Danlos syndrome (EDS), which is often caused by mutations within the α1(V) collagen gene (COL5A1)." (PMID 36553626, 2022). "Variants in COL3A1 and COL5A1, key genes in collagen synthesis and connective tissue integrity, suggest an overlap between SCAD and vascular connective tissue disorders such as Ehlers-Danlos syndrome." (PMID 40815415, 2025). "Heterotrimeric collagen V fibrils regulate the diameter of fibrillar collagen I fibrils in skin and mutations in COL5A1 and COL5A2 can result in classic Ehlers-Danlos syndrome, characterized by fragile skin, hyperextensible skin and impaired wound healing." (PMID 38559576, 2024). "COL5A1 and COL5A2 are involved in encoding type V collagen, and its mutation is related to Ehlers-Danlos syndrome." (PMID 35872873, 2022).
Ehlers-Danlos syndrome (continued). "It has been proved that the mutation of COL5A1 and COL5A2 leads to Ehlers-Danlos syndrome, a connective tissue disorder." (PMID 33860039, 2021). "Mutations in COL5A1 and COL5A2 genes resulting in haploinsufficiency or structural modifications of type V collagen are common causes for classical Ehlers-Danlos Syndrome (types I and II)." (PMID 28346524, 2017). "Defects in the proα1(V)- or the proα2(V)-chain, encoded by COL5A1 and COL5A2 respectively, lead to classic Ehlers-Danlos Syndrome (EDS), formerly known as EDS type I, “gravis” (MIM# 130000) and EDS type II, “mitis” (MIM# 130010)." (PMID 21611149, 2011). "A general connective tissue defect is seen in patients with Ehlers-Danlos syndrome (Classical EDS, which results from mutations in the COL5A1 gene), who deliver preterm due to CI or as polymorphisms in the collagen 1A1 gene (COL1A1) found in CI patients." (PMID 20673361, 2010). "Our PPI network analysis also revealed interactions between ZNF469 and CCT candidate genes, including COL5A1, COL1A1, and other genes that regulate eyeball development, such as VSX1 (causing KC and corneal dystrophy) and CHST14 (Ehlers-Danlos Syndrome candidate gene)." (PMID 40547359, 2025). "Similar resilience to matrix perturbation was observed in the meniscus of Col5a1+/− mice, a model for classical Ehlers-Danlos Syndrome (cEDS), illustrating an inherently robust mechanosensing framework to preserve normal homeostasis in various biological systems in vivo." (PMID 41292731, 2025). "Defects in type V collagen due to mutations in COL5A1 and COL5A2 are the cause of the classical type (types I and II) of the heritable connective tissue disorder Ehler-Danlos syndrome that confers an increased risk for PTD if the fetus is affected, especially from pPROM." (PMID 22208904, 2011). "Moreover, patients suffering from classic Ehlers-Danlos syndrome, a rare connective tissue disorder mainly caused by mutations in COL5A1 or COL5A2, do not appear to show ventricular malformations." (PMID 23574622, 2013). "COL5A1 expression in osteoblasts and vascular smooth muscle cells is induced by TGF-β1 and haplo-insufficiency leads to the heritable connective-tissue disorder Ehlers-Danlos syndrome that is characterized by an altered collagen-fibrillar structure of the dermis, joints, eyes and blood vessels." (PMID 16594992, 2006).
gastric cancer (32 papers, 2019 to 2025). A primary or metastatic malignant neoplasm involving the stomach. "COL5A1, encoding an alpha chain of type V collagen, was a promising prognostic marker considered to have a good potential for the treatment of patients with gastric cancer as well." (PMID 33178362, 2020). "Another in‐silico‐based study that analyzed multiple publicly available datasets identified collagen genes COL1A1, COL1A2, COL3A1, and COL5A1 as key CAF markers in gastric cancers." (PMID 39245631, 2025). "COL5A1, the final gene in our prognostic panel, is upregulated across multiple malignancies, including glioma, clear cell renal cell carcinoma, and gastric cancer." (PMID 40860666, 2025). "Molecular mechanism studies show that NAT10 directly binds to the 3′ UTR region of COL5A1 mRNA in an ac4C modification‐dependent manner, promoting COL5A1 expression and thus promoting gastric cancer cell metastasis and EMT137." (PMID 39764566, 2025). "We identified several genes, including FN1, COL1A2, THBS2, COL3A1, COL5A1, and BGN, which appear to be associated with poorer outcomes for stomach cancer patients." (PMID 38610959, 2024). "High expression of COL1A1, COL3A1, COL5A1, FN1, and SPARC was significantly associated with poor survival in gastric cancer patients (p < 0.05)." (PMID 35739492, 2022). "Among the six CAF markers, we identified COL1A1 and COL5A1 as the two markers which potentiated the poor prognostic impact of CAF infiltration most in gastric cancer." (PMID 35739492, 2022). "Moreover, NAT10 promotes gastric cancer by regulating COL5A1, and promotes bladder cancer progression by participating in DNA damage repair pathways." (PMID 40169553, 2025). "NAT10‐mediated COL5A1 acetylation promotes gastric cancer metastasis." (PMID 39640362, 2024). "For instance, NAT10 facilitates gastric cancer metastasis through N4-acetylated COL5A1." (PMID 38243170, 2024). "Previous studies have indicated COL5A1’s role in gastric cancer progression through acting as a ceRNA for miR-137-3p to promote FSTL1 expression and its association with ovarian cancer progression, taxol resistance, and immune cell infiltration in the tumor environment." (PMID 39850883, 2024). "Knockdown of COL5A1 inhibited the proliferation, invasion, and migration of gastric cancer cells, which could be rescued by the miR-137-3p inhibitor or overexpression of FSTL1." (PMID 35805015, 2022). "COL5A1 is also overexpressed in gastric cancer, which may regulate the proliferation of gastric cancer cells by affecting the tumor microenvironment and is associated with poor prognosis." (PMID 34777463, 2021). "A substantial number of studies have verified that COL5A1 is an essential factor for the metastasis of cells in gastric cancer, which may also be a new prognostic factor with respect to lung adenocarcinoma, breast cancer, tongue squamous cell carcinoma, and other tumors." (PMID 35530352, 2022). "Besides, COL5A1 can accelerate the growth and progression of gastric cancer." (PMID 34026819, 2021). "Finally, COL5A1 has been found to have associations with gastric cancer, non-small cell lung cancer, and renal cancer." (PMID 30962767, 2019). "This modification extends the half-life of COL5A1 mRNA, leading to increased expression of EMT markers Vimentin and MMP2, which promotes metastasis in gastric cancer." (PMID 40881352, 2025). "In gastric cancer, NAT10 directly interacts with the 3′UTR of COL5A1 mRNA, modulating its ac4C modification." (PMID 40881352, 2025). "NAT10-mediated ac4C of COL5A1 promotes metastasis and EMT in gastric cancer, and NAT10-mediated ac4C acetylation of mRNA promotes the development of bladder cancer." (PMID 40169553, 2025). "In this study, we identified the six key CAF markers namely COL1A1, COL1A2, COL3A1, COL5A1, FN1, and SPARC in gastric cancer that can be used as predictors of CAF infiltration and prognostic biomarkers in gastric cancer." (PMID 35739492, 2022).
gastric cancer (continued). "We identified ECM components COL1A1, COL1A2, COL3A1, COL5A1, FN1, and SPARC as the pivotal CAF markers in gastric cancer, which were separately reported as biomarkers of gastric cancer in different studies." (PMID 35739492, 2022). "Eight out of 38 upregulated genes in gastric cancer (ASPN, COL1A1, COL1A2, COL3A1, COL5A1, FAP, FN1, and SPARC) overlapped with the CAF markers list (circos plot on the left)." (PMID 35739492, 2022). "Our study revealed the COL1A1, COL1A2, COL3A1, COL5A1, FN1, and SPARC as the key CAF markers in gastric cancer." (PMID 35739492, 2022). "Previous studies have shown that COL5A1 may affect the development of a variety of cancers, such as breast cancer, gastric cancer, lung adenocarcinoma, oral squamous cell carcinoma and ovarian cancer; moreover, the expression level of COL5A1 was an independent prognostic factor." (PMID 33281878, 2020). "In gastric cancer, NAT10 promotes tumor metastasis by stabilizing ac4C modification on COL5A1 mRNA." (PMID 41426311, 2025). "One limitation to the study may be that only the TIDE algorithm predicted a poor prognostic impact for CAF infiltration in COL1A1, COL5A1, ITGA4, EMILIN1, and TSPAN9 multivariate Cox model in gastric cancer." (PMID 35739492, 2022). "Hence the module analysis strengthened the connection of the six CAF markers: COL1A1, COL1A2, COL3A1, COL5A1, FN1 and, SPARC, with the 3 KEGG pathways: ECM-receptor interaction, focal adhesion and, PI3K-Akt signaling pathway in gastric cancer." (PMID 35739492, 2022). "In addition, COL5A1 up-regulation predicted dismal prognostic outcome in renal clear cell carcinoma (RCCC), BC, OC, and gastric cancer (GC)." (PMID 36118855, 2022). "The results showed that 8 up-regulated genes (FN1, COL3A1, FBN1, BGN, COL5A2, THBS2, COL5A1 and SPARC) and 1 down-regulated gene (ATP4A) may be the central genes in gastric cancer." (PMID 32742441, 2020). "A previous study revealed that in gastric cancer (GC), NAT10 directly interacts with the 3'UTR of COL5A1 mRNA to regulate its ac4C modification, thereby promoting GC metastasis and EMT." (PMID 41316475, 2025). "Therefore, we tested whether the addition of TSPAN9 to the CO1A1, COL5A1, ITGA4, and EMILIN1 Cox model can decrease the poor prognostic impact of CAF infiltration in gastric cancer." (PMID 35739492, 2022).